SWAP70 (switching B cell complex subunit SWAP70)
Description:
Phosphatidylinositol 3,4,5-trisphosphate-dependent guanine nucleotide exchange factor (GEF) which, independently of RAS, transduces signals from tyrosine kinase receptors to RAC. It also mediates signaling of membrane ruffling. Regulates the actin cytoskeleton as an effector or adapter protein in response to agonist stimulated phosphatidylinositol (3,4)-bisphosphate production and cell protrusion (By similarity).
Synonyms: SWAP-70; KIAA0640; HSPC321
Tractability: Antibody: its Gene Ontology location is reachable by antibodies, with high confidence; UniProt places it where antibodies can reach, with medium confidence; the Human Protein Atlas places it where antibodies can reach. PROTAC: ubiquitination databases record sites on it; its protein half-life has been measured.
Gene: Protein-coding gene on chromosome 11 (9,664,072 to 9,752,993, forward strand). Ensembl gene ENSG00000133789.
Subcellular location: Cytoplasm; Cell membrane; Nucleus; Cell projection, lamellipodium; Cytoplasm, cytoskeleton
Subcellular location (Human Protein Atlas): Plasma membrane; Actin filaments
Pathways (Reactome):
Signal Transduction: RAC1 GTPase cycle; RAC2 GTPase cycle; RAC3 GTPase cycle
Gene Ontology:
Molecular function: cadherin binding; protein binding; guanyl-nucleotide exchange factor activity; ATP binding; calcium ion binding; DNA binding
Biological process: regulation of small GTPase mediated signal transduction; actin filament bundle assembly; negative regulation of actin filament depolymerization; negative regulation of cell-cell adhesion mediated by integrin; positive regulation of actin filament bundle assembly; positive regulation of cytosolic calcium ion concentration; positive regulation of mast cell chemotaxis; regulation of actin polymerization or depolymerization; regulation of protein localization
Cellular component: actin cytoskeleton; cytoplasm; nucleus; plasma membrane; postsynapse; cytosol; cytoskeleton; lamellipodium
Genetic constraint (gnomAD): Loss-of-function variants: 28 observed, 66.11 expected, observed/expected ratio (o/e) 0.42, 90% interval 0.31 to 0.58. The upper end of that interval is the gene's LOEUF score, 0.58, which puts it in group 2 of 6, group 1 being the genes least tolerant of losing a copy. Missense variants: 533 observed, 635.66 expected, observed/expected ratio (o/e) 0.84, 90% interval 0.78 to 0.9. Synonymous variants: 222 observed, 220.74 expected, observed/expected ratio (o/e) 1.01, 90% interval 0.9 to 1.12.
Homologues: Orthologues: chimpanzee SWAP70 (100% identical), macaque SWAP70 (99% identical), dog SWAP70 (96% identical), pig SWAP70 (96% identical), rabbit SWAP70 (96% identical), mouse Swap70 (95% identical), rat Swap70 (95% identical), guinea pig SWAP70 (93% identical), zebrafish swap70b (76% identical), tropical clawed frog swap70 (74% identical), zebrafish swap70a (61% identical), Caenorhabditis elegans F31D4.5 (15% identical). Paralogues in human: DEF6 (46% identical), PLEKHD1 (17% identical).
Diseases named in the same sentence as SWAP70 in open-access papers:
SWAP70 is named in the same sentence as 37 diseases in open-access papers, as found by Europe PMC text mining. Sharing a sentence is not in itself a finding about the gene and the disease. The quoted sentences say what the papers report.
glioma (5 papers, 2015 to 2024). A benign or malignant brain and spinal cord tumor that arises from glial cells (astrocytes, oligodendrocytes, ependymal cells). "We found that high SWAP-70 expression in high-grade glioma tissues was associated with a poor prognosis of glioma patients." (PMID 31832018, 2019). "High SWAP-70 expression in the high grade glioma tissues was associated with a poor prognosis in high-grade glioma patients, suggesting that high SWAP-70 expression is a poor prognostic marker in the high-grade glioma." (PMID 31832018, 2019). "GSAP and SWAP70 expressed similar levels in different cell lines, and the expression of the remaining three genes was lower in glioma cell lines." (PMID 36727078, 2022). "Another Rho GEF is SWAP-70 which is overexpressed in human high-grade glioma tissues and high-grade glioma patients." (PMID 32089990, 2020). "Further analysis of the relationship between SWAP-70 expression and the prognosis of glioma patients using online TCGA and GEO databases showed that patients with high SWAP-70 expression in glioma tissues had a poorer prognosis than those with low expression." (PMID 31832018, 2019). "Additionally, SWAP70, which is involved in cytoskeletal rearrangement, plays an important role in the oncogenesis of glioma and prostate cancer." (PMID 38157275, 2024). "SWAP-70 was highly expressed in the high-grade glioma tissues compared to normal brain tissues." (PMID 31832018, 2019). "SWAP70 also influences these processes in glioma and prostate cancer cells." (PMID 25889342, 2015).
lupus (5 papers, 2017 to 2025). "Subsequently, it was demonstrated that global heterozygous deficiency of IRF5 also reduces disease in the Lyn-deficient mouse lupus model, the gld.apoE-deficient mouse lupus model, and in the Swap70-deficient Def6-deficient mouse lupus model." (PMID 34197340, 2021). "On the other hand, it has been described that mice deficient in both SWAP-70 and its homolog DEF6 develop systemic lupus erythematosus, indicating that DEF6 expression might at least partially compensate for defects in Swap-70-/- mice." (PMID 35359955, 2022). "Notably, double knockout (DKO) of Def6 and SWAP70 in C57BL/6 mice results in development of lupus, predominantly in female mice as in human SLE21." (PMID 28811467, 2017). "POU2F2/OCT2, important for generation of ASCs; SWAP70, shown to influence ABC expansion; and AIM2, which positively regulated expansion of autoreactive B cells in a mouse lupus model, were increased in both blood and skin B cells in active cGVHD." (PMID 37129971, 2023).
Autoimmunity (3 papers, 2015 to 2025). The occurrence of an immune reaction against the organism's own cells or tissues. "Since we found Swap-70 to be expressed in activated Teff cells, our data suggest a scenario in which the function of SWAP-70 in Teff is crucial for the establishment of autoimmunity in the context of SWAP-70-deficient Treg cells." (PMID 35359955, 2022). "SWAP-70 has been implicated in the pathogenesis of autoimmune disorders, including MS." (PMID 41816749, 2025). "First, fertility, mortality and cellularity of lymphoid organs were analyzed, to assess whether SWAP-70-deficiency affects the overall fitness of these mice, and whether there are clinical signs of systemic or organ-specific autoimmunity." (PMID 35359955, 2022). "Although autoimmunity in DKO mice is accompanied by dysregulated IRF4 activity in both T and B cells, SWAP-70 is also known to regulate multiple aspects of DC biology leading us to directly evaluate DC development and function in these mice." (PMID 26544714, 2015).
prostate carcinoma (3 papers, 2015 to 2024). A carcinoma that arises from epithelial cells of the prostate gland. "A study of 75 clinical prostate specimens using SWAP70 immunohistochemical analysis showed that silencing SWAP70 significantly inhibited migration and invasion of prostate cancer cell lines." (PMID 34194957, 2021).
atherosclerosis (2 papers, 2022 to 2026). A disease characterized by the build-up of fatty material and calcium deposition in the arterial wall resulting in partial or complete occlusion of the arterial lumen. "New association signals from cross-ancestry GWASs included, for example, variants at PROCR, GRK5 and F11 (thrombosis), LPA and ATP2B1 (lipid metabolism, hypertension and atherosclerosis), SWAP70 (membrane ruffling) and LAMC1 (cerebrovascular matrisome)." (PMID 36180795, 2022).
cardiac hypertrophy (2 papers, 2024 to 2026). "FGFBP3 and switch-associated protein 70 (SWAP70) may protect against weight gain and cardiac hypertrophy, respectively." (PMID 39190027, 2024).
coronary heart disease (2 papers, 2019 to 2024). "Our study identified two proteins, PCSK9 and AIDA, linked to HF in patients with coronary heart disease (CHD), and four proteins, PCSK9, SWAP70, NCF1, and RELT, associated with HF in patients receiving antihypertensive medication." (PMID 38383373, 2024). "To demonstrate the value of the expanded database and additional functionality of PhenoScanner V2, we searched for ‘rs10840293’, ‘SWAP70’ and ‘coronary heart disease’." (PMID 31233103, 2019). "Two proteins (PCSK9 and AIDA) exhibited associations with HF in patients with coronary heart disease (CHD), and four proteins (PCSK9, SWAP70, NCF1, and RELT) were related with HF in patients receiving antihypertensive medication." (PMID 38383373, 2024).
essential hypertension (2 papers, 2022 to 2024). Hypertension that presents without an identifiable cause. "Additionally, it was observed that genetically predicted elevated levels of circulating SWAP70 were associated with a decreased risk of essential hypertension and HF in patients receiving antihypertensive medication." (PMID 38383373, 2024). "Furthermore, our results demonstrated that predicted higher levels of circulating SWAP70 were associated with an increased risk of essential hypertension and HF in patients receiving antihypertensive medication." (PMID 38383373, 2024).
lupus-like syndrome (2 papers, 2015 to 2021). "Here we have employed mice that lack the expression of DEF6 and SWAP-70, two molecules known to restrain IRF4 function in T and B cells, to explore the contribution of DC-IRF4 to the lupus-like syndrome that develops in these mice." (PMID 26544714, 2015). "Absence of DEF6 and SWAP-70, two homologous guanine exchange factors, in double-knock-out (DKO) mice leads to a lupus-like syndrome in females marked by accumulation of ABCs." (PMID 34376664, 2021).
rheumatoid arthritis (2 papers, 2022 to 2024). A chronic, systemic autoimmune disorder characterized by inflammation in the synovial membranes and articular surfaces. "Collectively, our data define a novel role of SWAP-70 in osteoimmunology and may thus have future implications for studies on bone disorders associated with functional defects of Treg cells, including rheumatoid arthritis." (PMID 35359955, 2022). "For example, we identified a shared genetic signal between plasma levels of switch-associated protein 70 (SWAP70) and rheumatoid arthritis (RA) (PP=99.1%)." (PMID 38429390, 2024).
thrombosis (2 papers, 2022 to 2024). "Among them, mutations in ABCA13, FLT1, NRP1, SWAP70 and SLC15A4 are strongly associated with immunity or proliferation, whereas mutations in VWF, SELP and EPHB2 are associated mainly with thrombosis." (PMID 39671267, 2024). "In addition, we found that a greater proportion of patients with thrombosis than patients without thrombosis carried EpHB2 mutations (p = 0.015), SWAP70 mutations (p = 0.039), ABCA13 mutations (p = 0.01) and SLC15A4 mutations (p = 0.004)." (PMID 39671267, 2024).
angioma (1 paper, 2015). "SWAP70 expression was also detected by immunohistochemistry in human-derived KS-positive lesions (as indicated by latent nuclear antigen (LNA) staining), as well as in non-KS, LNA-negative angioma." (PMID 25889342, 2015).
atrial fibrillation (1 paper, 2026). A disorder characterized by an electrocardiographic finding of a supraventricular arrhythmia characterized by the replacement of consistent P waves by rapid oscillations or fibrillatory waves that vary in size, shape and timing and are accompanied by an irregular ventricular response. "The effect of F11, SH3BGRL3, SPATA20 and SWAP70 on each subtype was mediated by Factor XI inhibitors, atrial fibrillation, type 2 diabetes and systolic blood pressure, respectively (P < 0.05)." (PMID 41488603, 2026).
breast carcinoma (1 paper, 2024). "SWAP-70–deficient breast cancer cells are impaired in migration as several assays showed." (PMID 38760173, 2024). "To identify the role of SWAP-70 in mouse breast cancer metastasis, we generated SWAP-70–deficient (KO) cell lines using the CRISPR/Cas9 system in the BALB/c-derived mouse breast cancer cell line 4T1, which resembles human metastatic triple-negative breast cancer cells." (PMID 38760173, 2024). "Breast cancer cell growth, migration, adhesion, and invasion assays revealed SWAP-70’s key role in these metastasis-related cell features and the requirement for SWAP-70 to bind F-actin." (PMID 38760173, 2024).
COVID-19 (1 paper, 2021). A disease caused by infection with severe acute respiratory syndrome coronavirus 2. "Indeed, expansion of T-bet+ B cells (including activated naïve and DN) and PBs, which in some cases can exhibit reprogramming potential and lower levels of SWAP-70, have all been observed in severe COVID-19 patients." (PMID 34376664, 2021).
glioblastoma (1 paper, 2019). The most malignant astrocytic tumor (WHO grade IV). "However, the mechanism by which SWAP-70 regulates the migration and invasion of glioblastoma (GB) cells has not been fully elucidated." (PMID 31832018, 2019).
ischemic stroke (1 paper, 2026). A stroke disorder caused by obstruction of blood flow to the brain, due to thrombotic (local blood clot formation) or embolic (due to a blood clot or other material traveling from another site) event. "We also found that SCARA5 and SWAP70 were related to stroke and ischemic stroke at the transcriptome level." (PMID 41488603, 2026). "In conclusion, we found causal evidence supporting three classic genes MMP12, F11 and SCARA5, and three novel genes SH3BGRL3, SWAP70 and SPATA20 were associated with the risk of ischemic stroke and their subtypes." (PMID 41488603, 2026).
psoriasis (1 paper, 2024). An autoimmune condition characterized by red, well-delineated plaques with silvery scales that are usually on the extensor surfaces and scalp. "Furthermore, this study marks the initial identification of several proteins—MAPRE1, SWAP70, VPS26A, BRD2, and B3GNT2—as potentially contributing factors in the pathogenesis of psoriasis." (PMID 39883516, 2024).
renal carcinoma (1 paper, 2025). A carcinoma arising from the epithelium of the renal parenchyma or the renal pelvis. "As a critical oncogenic molecule, miR-145 inhibits the proliferation, invasion, and metastasis of prostate, bladder, and renal cancers while inducing apoptosis in tumor cells by targeting and regulating oncogenic signaling pathways, such as PLD5, SWAP70, and STAT3." (PMID 40689207, 2025).
sarcoidosis (1 paper, 2022). Sarcoidosis is a multisystemic disorder of unknown cause characterized by the formation of immune granulomas in involved organs. "Furthermore, non-synonymous SNPs in LILRB2, GZMB, APOL1, CNN2, SWAP70, and CSF1R were shown in over 50% of sarcoidosis patients." (PMID 35860586, 2022).
Stroke (1 paper, 2026). Sudden impairment of blood flow to a part of the brain due to occlusion or rupture of an artery to the brain. "We identified 7 potential risk genes (MMP12, F11, SH3BGRL3, ENGASE, SCARA5, SWAP70 and SPATA20) of stroke with altered protein abundances in the plasma." (PMID 41488603, 2026). "The PWAS identified 7 genes (MMP12, F11, ENGASE, SH3BGRL3, SPATA20, SWAP70, SCARA5) whose cis-regulated plasma protein levels were associated with stroke and its subtypes at a FDR of P < 0.05." (PMID 41488603, 2026). "This analysis was restricted to four genes, F11, SWAP70, SH3BGRL3 and SPATA20, which showed evidence of an effect in both MRs with risk factors and stroke outcomes." (PMID 41488603, 2026). "We found that the protein abundance of seven genes (MMP12, F11, SH3BGRL3, ENGASE, SCARA5, SWAP70 and SPATA20) in the plasma was associated with stroke and its subtypes, and six genes (MMP12, F11, SH3BGRL3, SCARA5, SWAP70 and SPATA20) causally related with stroke and its subtypes." (PMID 41488603, 2026). "Interestingly, two genes identified in TWAS (SWAP70 and SPATA20) were also significant in the AIS and SVS PWAS, respectively, suggesting joint evidence from PWAS and TWAS for its role in stroke etiology." (PMID 41488603, 2026).
tumor (11 papers, 2010 to 2025). "The results show a greatly impaired ability of SWAP-70–deficient tumor cells to extravasate; for except one mouse with only two extravasating/extravasated cells detected, there were no extravasating mutant cells." (PMID 38760173, 2024). "Because lung and bone microenvironments including extracellular matrix are different, and yet, in both tissues, metastasis of SWAP-70–deficient tumor cells is reduced, this suggests a rather general metastasis-reducing feature of SWAP-70 deficiency." (PMID 38760173, 2024). "A study reported that mutation of SWAP-70 can transform mouse embryo fibroblasts and promote the growth of tumor cells." (PMID 32404198, 2020). "Although studies have reported that SWAP-70 regulates cellular movement and tumor-cell migration and invasion, the underlying mechanisms have not been extensively studied." (PMID 31832018, 2019). "We suggest that the multifold effects of SWAP-70 promoting F-actin stabilization and thus changes in its dynamics support tumor cell metastasis and thus define a novel metastasis-promoting mechanism." (PMID 38760173, 2024). "The Ctrl group showed a threefold and an eightfold higher number of GFP-positive cells compared with the G1KO and G3KO groups, respectively, indicating that SWAP-70 is crucial for blood vessel–borne tumor cells to accumulate in the lung." (PMID 38760173, 2024). "Treatment of tumor cells with the motility- and metastasis-modulating drug 12(S)-HETE caused SWAP-70 translocation to membrane ruffle-like structures where the protein dimerizes, binds, and bundles actin." (PMID 38760173, 2024). "Cell culture, and biophysical and mouse data show that the F-actin modulator protein SWAP-70 supports tumor cell metastasis." (PMID 38760173, 2024). "In summary, these data show that the SWAP-70 F-actin binding domain and thus the interaction of SWAP-70 with F-actin are critical for cell migration, adhesion, cell mechanics, and homing of the tumor cells into the lung." (PMID 38760173, 2024). "Several upregulated proteins in the reintervention group, including SNRPD1, SRSF10, SWAP-70, and PSMB1, are associated with tumor progression in other cancer types." (PMID 38157275, 2024). "In this report, we demonstrate that the interaction of SWAP-70 with F-actin contributes substantially to tumor metastasis." (PMID 38760173, 2024). "Clearly, SWAP-70 is also required for efficient metastasis in the later steps, that is, from the presence of tumor cells in the bloodstream to establishing metastases." (PMID 38760173, 2024). "We also found that several other key actors of macropinocytosis, such as Rab34, Arp2/3 complex and SWAP70, were significantly overexpressed according to the grade of the tumor (Table A1)." (PMID 30909495, 2019). "SWAP-70 is involved in tumor cell migration and invasion in GB; however, the underlying mechanism has not been fully clarified." (PMID 31832018, 2019). "Because F-actin rearrangement is likely to be related to cell transformation, these findings support the idea that SWAP-70 contributes to tumor formation in some way." (PMID 21152038, 2010). "The expression of SWAP-70 correlated with the severity of glioblastoma and was shown to affect in vitro extracellular matrix degradation and invasion, as well as anchorage-independent growth of tumor cell lines." (PMID 38760173, 2024). "The expression of EMP3, GSAP, SLC2A10, and SWAP70 was higher in tumor periphery." (PMID 36727078, 2022). "Blockade of SWAP70 function could be of therapeutic value to prevent permeability and activation of endothelial cells and thus hinder tumor angiogenesis." (PMID 25889342, 2015). "Our previous study demonstrated that tumor suppressive miRNAs, such as miR-1, miR-133a, and miR-145 functioned through repression of LIM and SH3 protein 1 (LASP1), transgelin-2 (TAGLN2), and Switch associated protein 70 (SWAP70)." (PMID 22179486, 2012). "Overexpression of SWAP-70 has been often seen in malignant tumor and in various tumor cell lines." (PMID 21152038, 2010).